AQP7 (aquaporin 7)
Diseases named in the same sentence as AQP7 in open-access papers (continued):
Sharing a sentence is not in itself a finding about the gene and the disease.
cancer (17 papers, 2015 to 2026). A tumor composed of atypical neoplastic, often pleomorphic cells that invade other tissues. "It is noteworthy that prior to the clinical manifestation of cancer, genes involved in lipid metabolism and adipogenesis are upregulated in susceptible breast tissues in women, with a particularly significant increase observed in AQP7 mRNA levels in these tissues." (PMID 39456161, 2024). "Moreover, a cancer cell line expressing AQP7 treated with Z433927330 has decreased proliferation compared to control, suggesting that AQP7 is a cancer susceptibility factor that could be further explored as a therapeutic target." (PMID 38319972, 2024). "Here, we report structural analyses of AQP7 in complex with the inhibitory compound Z433927330 and a proliferation assay showing a reduction in proliferation of cancer cells treated with Z433927330." (PMID 38319972, 2024). "We determined that the expression level of AQP7 mRNA in cancer tissues was often lower than that in the corresponding normal tissues, but protein-level evidence still needs to be discovered." (PMID 35972604, 2022). "Therefore, further research is needed to elucidate the precise regulatory mechanisms of AQP7 involvement in cancer occurrence and development." (PMID 39456161, 2024). "AQP7 is also thought to play a role in the occurrence and development of cancer." (PMID 39456161, 2024). "Recently it was reported that AQP7 is a vulnerability in cancer." (PMID 38319972, 2024). "ROC plot analysis identified AQP7 as a potential cancer biomarker." (PMID 39123442, 2024). "AQP7 has different expression levels between tumors and corresponding normal tissues, implying that it may affect the prognosis of cancer." (PMID 35972604, 2022). "The relationship between the expression levels of AQP7 and AQP10 and the prognosis of cancer remains ambiguous because there have been only a few attempts to examine AQP7 and AQP10 in cancer, and existing research was limited to the mRNA level." (PMID 35972604, 2022). "This overlap includes numerous PPARG target genes, including ANGPTL4 and AQP7, which were two of the six most highly induced genes in the human PPFP carcinomas." (PMID 26595524, 2015). "The homogenous expression of AQP3, AQP7 and AQP9 suggests that the cancer cells have a high capacity for glycerol uptake, which may contribute to the increased energy consumption of the cancer cells." (PMID 37681917, 2023). "Moreover, the role of AQP10 in cancer has never been satisfactorily elucidated, which means that more research regarding AQP7 and AQP10 in cancer is needed." (PMID 35972604, 2022). "Considering that gold compounds affect both AQP3 and AQP7, this POT may be advantageous as a drug candidate for AQP3-overexpressing cancers." (PMID 32252345, 2020). "Thus, the homogenous expression of AQP3, AQP7 and AQP9 may aid the cancer cells in their adaptations to high osmotic stress as well as facilitate H2O2-mediated signaling—both of which may aid cancer cell survival." (PMID 37681917, 2023). "Interestingly, while exploring the specific mechanism of metformin in decreasing blood glucose level and even cancer inhibition, some researchers found that MAPK signaling pathway could be inhibited by metformin and pancreatic aquaporin 7 (AQP7) was then reactivated to allow insulin secretion." (PMID 36973739, 2023).
metabolic disease (6 papers, 2018 to 2025). A congenital disorder (due to inherited enzyme abnormality) or acquired (due to failure of a metabolically important organ) disorder resulting from an abnormal metabolic process. "The specific implications of AQP7 modulation for the adipose tissue and metabolic health will require further investigations, including AQP7 modulation in metabolic disease contexts." (PMID 41203811, 2025). "AQP7 and AQP9 represent glycerol channel in adipose tissue and liver and have been associated with metabolic diseases." (PMID 30598999, 2018).
infection (2 papers, 2024 to 2025). The state of being infected such as from the introduction of a foreign agent such as serum, vaccine, antigenic substance or organism. "To further elucidate the role of AQP7 in MAPK expression, autophagy, and apoptosis in the presence of palmitate, we established RIN‐m5f cell lines with stable overexpress of AQP7 using lentiviral infection." (PMID 40127965, 2025). "To assess the impact of AQP7 on MAPK signaling, we established RIN‐m5f cell lines with stable knockdown of AQP7 via lentiviral infection." (PMID 40127965, 2025).
heart diseases (1 paper, 2024). "AQP7 also plays a significant role in the treatment of heart diseases." (PMID 39456161, 2024).
vasculopathy (1 paper, 2025). "When compared to Aqp7+/+ mice, the VAT of the Aqp7−/− mice showed a higher intensity of CD31 marking the capillaries and an increased number of stiffened vessels, characterized by a ring of α-SMA suggesting enhanced angiogenesis and vasculopathy." (PMID 41203811, 2025).
AQP7 also shares sentences with these, for which no sentence is quoted: metabolic syndrome (3 papers); Adult onset (2); Glucose intolerance (2); ulcerative colitis (2); acute renal failure (1); Asthenozoospermia (1); atrophic gastritis (1); cardiovascular diseases (1); congestive heart failure (1); ductal carcinoma (1); endometrial cancer (1); eosinophilia (1); epidermoid carcinoma (1); Epididymis (1); hydronephrosis (1); leukemia (1); liver cirrhosis (1); lung carcinoma (1); mesothelioma (1); renal oncocytoma (1); renal pelvis urothelial carcinoma (1); thyroid cancer (1); triple-negative breast carcinoma (1).